DAPK1 (death associated protein kinase 1)
Diseases named in the same sentence as DAPK1 in open-access papers (continued):
Sharing a sentence is not in itself a finding about the gene and the disease.
tumor (continued). "However, at day three after transplantation, tumor areas reached nearly equal fluorescence intensities suggesting that DAPK1 ko cells have a better early adaptation capability to the 3D environment." (PMID 31772156, 2019). "In addition, the DAPK1 SNV rs11141901 was significantly associated with both co-morbidity and tumor differentiation." (PMID 31528229, 2019). "Notably, just like the CAM tumors, HCT116 cells generated dense tumor masses while DAPK1 ko clones formed more loosely packed and more spacious tumors as reflected by a more diffuse green fluorescence." (PMID 31772156, 2019). "DAPK1 loss was associated with high-grade tumor budding (50% of evaluated tumors) demonstrating that every second HPF of DAPK1 negative tumors was given a high-grade score whereas 89% of all HCT116 wildtype tumors were low-grade budders." (PMID 31772156, 2019). "Overexpression or activation of DAPK1, as a tumor suppressor, is involved in cell death." (PMID 31336860, 2019). "Results exposed significantly higher average radiant efficiency (**P < 0.01) within animals loaded with clone 21/9-derived DAPK1 ko tumors suggesting that DAPK1 ko cells showed more disseminating tumor cells, preferentially accumulating in the liver, heart, and brain of the chicken embryo." (PMID 31772156, 2019). "Accumulating evidence suggest that DAPK1 plays an important role in tumor suppression." (PMID 28231808, 2017). "In turn, using a monolayer wound healing assay siRNA-mediated knockdown of DAPK1 clearly increased tumor cell migration of ΔpBK-ITIH5 clone #7 compared to corresponding cells transfected with the non-silencing control siRNA (nc-control siRNA) that served as negative control." (PMID 28231808, 2017). "Using the median expression as the cut-off point, we found that 67% of the healthy specimens and 70% of the adjacent non-tumor expressed DAPK1 at a high level, but only 23% and 35% of cirrhotic and tumor specimens, respectively, expressed DAPK1 at a high level." (PMID 28740751, 2017). "Again in this study the tumour areas were scaled and compared with vimentin and DAPK1 serum levels." (PMID 28616237, 2017). "As a well-known tumor suppressor gene, DAPK1 expression can suppress tumor growth and metastasis." (PMID 28934284, 2017). "Changes in the expression of genes involved in apoptosis allow concluding about the activation of intrinsic mitochondrial pathway in tumor tissue after exposure to RNase A. We detected an upregulation of the genes Pycard, Plekhf1, and Dapk1, which activate the mitochondrial apoptotic pathway." (PMID 29108266, 2017). "In addition we showed, both in vitro and in xenograft models, that combining inhibition of DNA methylation with an anti‐netrin‐1 antibody resulted in the re‐expression of netrin‐1 and DAPK1 and led to tumor cell death and tumor growth inhibition." (PMID 27378792, 2016). "However, the apoptosis-related gene DAPK-1 was more often methylated in the cancerous tissues in the N3 category of the TNM classification (when tumor metastasis is found in ≥ 7 regional lymph nodes) than in those in the N0–2 category (p = 0.05)." (PMID 26810771, 2016). "Therefore, we evaluated the possible associations between the frequency distributions of DAPK-1, MLH1, and MGMT methylation and the Lauren morphological tumor classification." (PMID 26810771, 2016). "Furthermore, we observed that DAC treatments were associated with the re‐expression of DAPK1, netrin‐1, and UNC5B by the IHC staining of tumor sections." (PMID 27378792, 2016). "We also found that these anti-tumor effects on RCC cells caused by CYP1B1 depletion may be due to alteration of CDC20 and DAPK1 expression based on gene microarray and confirmed by real-time PCR." (PMID 26626260, 2015). "A positive connection between DAPK1 and autophagy/tumor suppression has been established." (PMID 26097870, 2015).
tumor (continued). "Thus, 20 studies (74%) evaluating DAPK1 promoter methylation both in tumor and in healthy control samples were included in the present meta-analysis." (PMID 26267895, 2015). "The correlation between methylation status of DAPK1 and tumor progression in RCC has been demonstrated, although other studies have shown that its expression may not be regulated by DNA promoter methylation." (PMID 26626260, 2015). "The silencing of DAPK1 can result in uncontrolled cell proliferation, indicating that it may have a role in tumor suppression." (PMID 25435999, 2015). "DAPK1 has been demonstrated to act as a key tumor suppressor gene in CLL." (PMID 23383130, 2013). "A few oncogenes (e.g. phosphatidylinositol 3-kinase, activated AKT1) inhibit autophagy, while numerous tumor suppressors (e.g. BH3-only proteins, death-associated protein kinase-1, PTEN, tuberous sclerosic complex 1 and 2, TSC1 and TSC2 and LKB1/STK11) induce autophagy." (PMID 21191146, 2010). "Death-associated protein kinase-1 methylation was more frequent in malignant than in benign tissue but did not correlate with a higher tumour stage or differentiation grade." (PMID 17133271, 2006). "Moreover, a few publications, pointing to findings for the DAPK-1 gene, have postulated that the methylation frequency or level correlates with the biological behaviour of the tumour disease." (PMID 17133271, 2006). "Therefore, DAPK1 can not only act as a tumor suppressor but also promote metastasis." (PMID 39057063, 2024). "That study found that DAPK1 could inhibit ZEB1 expression in PCa mouse tumor tissues." (PMID 39057063, 2024). "In addition, DAPK1 is a tumor suppressor that inhibits the transformation of normal cells into abnormal cells in the early stages of tumorigenesis, and inhibits tumor metastasis through its effect on the cytoskeleton." (PMID 36386181, 2022). "Proteins DAPK1 (Death-associated proteinkinase 1), MGMT (Methylated-DNA-protein-cysteine methyltransferase),and SOCS1 (Suppressor of cytokine signaling 1)are considered tumor suppressors, and their low expressionin carcinomas correlates with disease progression." (PMID 36714033, 2022). "It was found that DAPK1 expression could significantly inhibit the tumor growth and metastasis." (PMID 34335109, 2021). "Since CUX1 has been identified as transcriptional repressor and its activity induced tumour cell survival and migration, accompanied by tumour progression and shortened survival in several tumour entities, DAPK1 may be an integral part of the oncogenic CUX1-mediated orchestra." (PMID 32707646, 2020). "DAPK1 loss might promote dissemination seen as increase in number of tumor buds and remodeling of the CAM collagen matrix triggering the colonization of tumor cells at a secondary site since we found significantly more metastasis in chicken embryonic organs from DAPK1 ko xenografts." (PMID 31772156, 2019). "Thus, one of the tumor suppressor functions of DAPK1 might be partly mediated by suppressing the metastasis associated TACSDT2." (PMID 31772156, 2019). "Therefore, silencing of DAPK1 may result in uncontrolled cell proliferation, indicating that this gene may have a role in tumor suppression." (PMID 30409182, 2018).
tumor (continued). "Therefore, the use of selective inhibitors might shed light on the exact participation of DAPK1 in tumor development." (PMID 30287790, 2018). "However, the association between DAPK1 levels and the tumour grades was not statistically significant (p = 0.562)." (PMID 28616237, 2017). "Furthermore, the silencing of DAPK1 or UNC5B mRNA prevented the inhibition of tumor growth induced by the combination treatment, further confirming our working hypothesis." (PMID 27378792, 2016). "Functional restoration of DAPK1 was conducted in HGSOC cell lines and patient-derived primary tumor cells using vector-based expression or in vitro-transcribed (IVT) DAPK1 mRNA, including the application of truncated DAPK1 (ΔDAPK1) forms." (PMID 40563561, 2025). "Our goal was to reactivate specific DAPK1 functions by using the ΔDAPK1-mRNA transfection of HGSOC cell lines and primary tumor cells." (PMID 40563561, 2025). "Among the 13 ferroptosis- and lipid metabolism–related signature genes, CPA3, DAPK1, and ANGPTL4 exhibited significant positive correlations with most immune checkpoint genes, suggesting that higher expression of these genes may be associated with an immune-activated tumor microenvironment." (PMID 41425595, 2025). "In contrast, DAPK1, ASPG, and CPA3 were more highly expressed in normal tissues than in tumor tissues." (PMID 41425595, 2025). "The results showed that all genes exhibited significant differential expression in tumor tissues; however, only four genes (CAPS, DAPK1, P4HA1, and PCED1A) demonstrated independent prognostic value." (PMID 40463370, 2025). "DAPK1 is predicted to interact with CDKN2A, an essential tumor suppressor gene involved in cell cycle regulation and cellular senescence." (PMID 40611883, 2025). "DAPK1 also affects signaling pathways involved in tumor initiation and progression, such as Wnt/β-catenin, NF-κB, and MAPK pathways, impacting tumor proliferation, invasion, metastasis, and drug resistance." (PMID 39926603, 2024). "At the same time, OLP expressed statistically significantly more DAPK-1 than OSCC, which makes sense since in cancerous lesions, tumor-suppressing genes are expected to be silenced." (PMID 39553125, 2024). "Surprisingly, multiple previously reported tumor suppressors of KIRC were found in these downregulated genes, including SOX6, DAPK1, PDZK1, TXNIP, DAB2IP, and CMTM4." (PMID 37737260, 2023). "These included well-known receptor tyrosine kinase genes (EGFR, TEK and OSMR) that activate MAPK and PI3K signaling pathways, and other tumor-promoter genes (ATP8B2, DAAM1, SLAMF8 and SRGN) as well as tumor-suppressor genes (A2M, DAPK1, RASSF8 and SOCS3)." (PMID 37190308, 2023). "The function of DAPK1 and ULK2 reported previously are consistent with the results of our study, which suggest tumor-suppressive roles in NB." (PMID 36530992, 2022). "Numerous genes that inhibit tumour growth, such as CDKN2B, CDKN2A, CDH1, DAPK1, SOCS1, and SHP1, were rendered inactive as a result of DNA hypermethylation at the CpG islands that are associated with their promoters." (PMID 36359286, 2022). "The methylation level in the methylated EOC tumor samples ranged from 4 to 97% for HOXA9; 7–89% for HIC1; 4–97% for SOX1; 4–95% for DAPK1; 5–97% for SFRP1; 6–99% for SPARC and 4–98% for RASSF1A gene, respectively." (PMID 34778370, 2021). "The promoter methylation levels of selected candidate genes (RASSF1A, DAPK1, SOX1, HOXA9, HIC1, SPARC, and SFRP1) were quantitatively evaluated by MethyLight in tumor DNA samples of patients with EOC." (PMID 34778370, 2021). "As reported, TPPP3, DOCK2, and EIF3H act as oncogenes by suppressing apoptosis of cancer cells, while RNF128, DAPK1, and SYT7 function as tumor suppressors by promoting apoptosis of many types of cancer cells." (PMID 33509274, 2021).
tumor (continued). "Five molecules (DAPK1, TIMP3, GRIN2B, SLC5A8, and CDH1) are tumor suppressor genes consistently downregulated and/or hypermethylated in GC and in H. pylori infected children." (PMID 32117120, 2020). "In our previous report, the association between DAPK1 and tumour grades could not be established." (PMID 32566040, 2020). "The significant genes observed were PYHIN1, IKZF1, CASP8, DAPK1 and SMCHD1 expression in tumor samples." (PMID 30867653, 2019). "The most frequently differentially hypomethylated CpG islands different between the normal and tumor tissues were TACSTD2, followed by SIM2 and DAPK1." (PMID 31675985, 2019). "While tumor promoting genes such as AGR2 were downregulated, known tumor suppressor genes like NDRG2 and DAPK1 were upregulated 4.3- and 4.6-fold, respectively." (PMID 28231808, 2017). "We studied the promoter regions of two genes that play important tumour suppressor roles in cancer, CDKN2B and DAPK1." (PMID 28392841, 2017). "Apoptosis related genes such as transcripts of DAPK1 (up) and NT5E (down), matched with the histochemical findings showing increased amounts of apoptotic cells in A2M* treated tissue slices and tumor xenografts." (PMID 29281661, 2017). "In addition, the association of DAPK1 methylation with the risk of gastrointestinal cancer was most notable in Asian patients and in CRC patients, which suggests that the pathogenic role of DAPK1 methylation in different geographical regions and tumor locations of gastrointestinal cancer vary." (PMID 28934284, 2017). "The meta-analysis of p14, p15, p73, APC, SOCS1, MGMT, SFRP1, PRDM2, DAPK1, RARβ, IGF2 and hMLH1 genes methylation was performed between HCC tumor tissues vs adjacent tissues and HCC tumor tissues vs normal tissues." (PMID 27835605, 2016). "Our meta-analysis was unable to find any statistical significance between HCC tumor tissues and adjacent tissues for the methylation of the remaining four genes, including MGMT, DAPK1, IGF2 and RB1." (PMID 27835605, 2016). "Although it shows significant structural differences from DAPK1, the founding member of this protein family, DAPK2 is also thought to be a putative tumour suppressor." (PMID 25741596, 2015). "In only 59 % (10/17), 53 % (9/17), 41 % (7/17), 38 % (6/16) and 35 % (6/17) of the tumor samples, RASSF1A, HIN-1, MGMT, DAPK1 and CCND2 promoters showed methylation status ≥ LOQ." (PMID 26370119, 2015). "Most of the tumors showed homogenous methylation of DAPK1 and MGMT, in some tumor tissues the promoter of these genes was methylated heterogeneously." (PMID 26370119, 2015). "The methylation status of RASSF1A, DAPK1 and CCND2 in tumor-adjacent tissues was significantly different from that in tumors." (PMID 26370119, 2015).
tumor (continued). "When the tumours were grouped according to their differentiation grade, the median NIM was 20% (53.4%) for APAF-1 in the G1/2 (G3) group and 34.1% (3.6%) for DAPK-1 in the pTa tumours." (PMID 17133271, 2006). "For the muscle-invasive tumour group (⩾pT2, only G3 tumours), the median NIM levels were 97.5% for APAF-1 and 15.8% for DAPK-1." (PMID 17133271, 2006). "In the G1/2 (G3) group of pT1 tumours, the median NIM was 53.5% (71%) for APAF-1 and 18.3% (24%) for DAPK-1." (PMID 17133271, 2006). "Genes like DAPK1, LRPPRC, RAB6C, and ZNF471 are found to be the targets of promoter hypermethylation that leads to the altered gene expression patterns that help in growth of tumours." (PMID 41487403, 2026). "By designing and delivering a truncated, catalytically active form of DAPK1 (∆DAPK1‐mRNA), we successfully reactivated its pro‐apoptotic functions in HGSOC cells, including paclitaxel‐resistant models and primary patient‐derived tumor cells." (PMID 40391786, 2025). "To investigate the reactivation of tumor suppressors via mRNA-based delivery, we utilized an in vitro transcription (IVT) system driven by a T7 RNA Polymerase promoter in a bacterial vector to generate truncated human DAPK1 mRNAs." (PMID 40563561, 2025). "In particular, the more intense protein expression in NOM, non-dysplastic OL, and mildly dysplastic OL aligns with the tumor-suppressing function of DAPK-1, which is expected to be expressed in these conditions of the oral epithelium." (PMID 40104466, 2025). "While a higher proportion of C1 DAPK1+ Macrophages was observed in the tumor core, statistical analysis did not reveal significant differences." (PMID 39926603, 2024). "In addition, we noted that in tumor samples the expression level of MEG3, TIMP, DAPK1 and SOX1 was lower, while the expression of MLH1 and MALAT1 was higher in comparison to the normal samples." (PMID 35682732, 2022). "Additionally, we found BECN1, DAPK1, VAMP7 and SIRT1 genes were correlated significantly with survival status, gender, primary tumor and tumor stage (all P < 0.05)." (PMID 32998713, 2020). "In this regard it was not surprising that DAPK1 was nearly lost in tumor buds at the invasion front of CRC." (PMID 31772156, 2019). "Vimentin concentration was highest in grade 3 tumours followed by grade 2 and 1 but that for DAPK1 was not significant." (PMID 28616237, 2017). "DAPK-1 and RASSF-1α genes play important role in growth inhibition and apoptosis of tumor cells." (PMID 28435431, 2017). "In the middle third, DAPK-1 promoter methylation was related to more-advanced disease in the lymph nodes (N2–3 compared with N0–1 [p = 0.02]) and advanced tumor stage (stage III rather than stages I–II [p = 0.05])." (PMID 26810771, 2016). "To date, the high CpG island methylation intensity of some tumor suppressors, RASSF1A, WIF1, DAPK1 and RARβ2, have been assessed by MS-HRM assays in NPC, so it is necessary to define whether DNA methylation of these promoters is also mediated by LMP1." (PMID 27223069, 2016). "In addition to DAXX, immunohistochemistry studies will include DAPK1 and DAPK3 so as to establish a relationship between DAXX and the DAPK1/3 tumor suppressors." (PMID 26097870, 2015). "In conclusion, the current study presents a typical trend for the association between the presence of DAPK1 promoter methylation and a variety of BCR-ABL mutations, regardless of any characteristics of the CML patients, such tumor stage, gender or age." (PMID 25435999, 2015).